ZBTB5 (zinc finger and BTB domain containing 5)
Description:
May be involved in transcriptional regulation.
Synonyms: KIAA0354
Tractability: PROTAC: UniProt records ubiquitination sites on it; ubiquitination databases record sites on it.
Gene: Protein-coding gene on chromosome 9 (37,437,687 to 37,468,850, reverse strand). Ensembl gene ENSG00000168795.
Subcellular location: Nucleus
Subcellular location (Human Protein Atlas): Nuclear bodies; Nucleoplasm; Golgi apparatus
Gene Ontology:
Molecular function: DNA-binding transcription repressor activity, RNA polymerase II-specific; protein binding; RNA polymerase II transcription regulatory region sequence-specific DNA binding; DNA-binding transcription factor activity, RNA polymerase II-specific
Biological process: negative regulation of transcription by RNA polymerase II; regulation of transcription by RNA polymerase II
Cellular component: nucleus; chromatin
Genetic constraint (gnomAD): Loss-of-function variants: 6 observed, 17.91 expected, observed/expected ratio (o/e) 0.34, 90% interval 0.18 to 0.66. The upper end of that interval is the gene's LOEUF score, 0.66, which puts it in group 2 of 6, group 1 being the genes least tolerant of losing a copy. Missense variants: 346 observed, 415.89 expected, observed/expected ratio (o/e) 0.83, 90% interval 0.76 to 0.91. Synonymous variants: 135 observed, 151.98 expected, observed/expected ratio (o/e) 0.89, 90% interval 0.77 to 1.02.
Homologues: Orthologues: chimpanzee ZBTB5 (99% identical), macaque ZBTB5 (99% identical), dog ZBTB5 (97% identical), rabbit ZBTB5 (95% identical), pig ZBTB5 (95% identical), mouse Zbtb5 (93% identical), rat Zbtb5 (93% identical), tropical clawed frog zbtb5 (77% identical), Drosophila melanogaster klu (14% identical), Caenorhabditis elegans klu-2 (9% identical), Drosophila melanogaster CG4318 (7% identical). Paralogues in human: ZBTB7A (18% identical), ZBTB43 (16% identical), ZNF367 (9% identical), ZNF740 (5% identical).
Diseases named in the same sentence as ZBTB5 in open-access papers:
ZBTB5 is named in the same sentence as 10 diseases in open-access papers, as found by Europe PMC text mining. Sharing a sentence is not in itself a finding about the gene and the disease. The quoted sentences say what the papers report.
non-small cell lung carcinoma (2 papers, 2021 to 2025). A group of at least three distinct histological types of lung cancer, including non-small cell squamous cell carcinoma, adenocarcinoma, and large cell carcinoma. "For example, the highly differential model for SMG1 is sepsis, the model for SLC25a52 is secondary renal amyloidosis, and the model for Zbtb5 is non-small-cell lung cancer." (PMID 34440578, 2021). "Moreover, ZBTB5 is involved in processes promoting cisplatin resistance in non-small cell lung cancer via a lncRNA (LINC00221)." (PMID 40353861, 2025).
muscle cancer (1 paper, 2025). A malignant neoplasm affecting the skeletal or smooth muscles. "It was shown that ZBTB5 expression is higher in retinoblastoma and muscle cancer tissues and is located in the nucleus." (PMID 40353861, 2025).
nephronophthisis (1 paper, 2025). Progressive tubulointerstitial injury, inherited in an autosomal recessive pattern, caused by mutations in genes involved in ciliary function, which may result in an end stage renal failure. "GLIS2 and ZBTB5, poorly characterized TFs, are implicated in processes like epithelial–mesenchymal transition and nephronophthisis but not in the NF-κB system." (PMID 39753783, 2025).
cancer (3 papers, 2016 to 2025). A tumor composed of atypical neoplastic, often pleomorphic cells that invade other tissues. "Transcription factors such as HMBOX1, DDX5, and ZBTB5, which were identified to be co-regulated by miR-20a and miR-15b, have implication on cancer progression." (PMID 31602261, 2019).
ZBTB5 also shares sentences with these, for which no sentence is quoted: chronic myeloid leukemia (1 paper); metastatic tumors (1); polycythemia vera (1); retinoblastoma (1); Sepsis (1); thyroid cancer (1).